MAF (MAF bZIP transcription factor)
Diseases named in the same sentence as MAF in open-access papers (continued):
Sharing a sentence is not in itself a finding about the gene and the disease.
cataract (6 papers, 2005 to 2026). Partial or complete opacity of the crystalline lens of one or both eyes that decreases visual acuity and eventually results in blindness. "When adult c-MAF conditional knockout mice were systemically deficient in c-MAF, they survived; however, they developed cataracts owing to lens maintenance failure." (PMID 37895232, 2023). "Hence, both gain-of-function and loss-of-function (targeted disruption) mutations of MAF cause lens diseases in mammals, including cataracts." (PMID 41542625, 2026). "MAF regulates the development of embryonic lens fibre cells, and defects in this gene lead to the development of cataracts, which are a frequent complication in older age." (PMID 35390271, 2022). "This approach endorsed an important interest considering involvement of MAF (MAF bZIP transcription factor; OMIM 177075), which is associated with juvenile-onset pulverulent cataract as well as congenital cerulean cataract (Cataract Multiple Types)." (PMID 33466592, 2021).
congenital cataracts (6 papers, 2014 to 2023). "For mutations in the transcriptional activation domain, c-MAF was detected as the causative gene for Aymé–Gripp syndrome resulting in congenital cataracts, deafness, mental retardation, epilepsy, and skeletal dysplasia." (PMID 37895232, 2023). "Among the many genes associated with congenital cataracts is the transcription factor gene MAF (v-maf avian musculoaponeurotic fibrosarcoma oncogene homolog, OMIM 177075, NM_005360.4)." (PMID 28482824, 2017). "There were no pathological mutations in known genes associated with non-syndromic congenital cataracts, like CRYB, CRYG, Cx43, Cx46, Cx50, MIP, PITX3, MAF, HSF4, and so on." (PMID 28076398, 2017). "Most genes are associated with isolated congenital cataracts while mutations in the transcription factor genes PAX6, FOXE3, EYA1, MAF, and PITX3 lead to congenital cataract with ASD." (PMID 24555714, 2014).
ovarian carcinoma (6 papers, 2010 to 2024). A malignant neoplasm originating from the surface ovarian epithelium. "The prognostic information of our five hub genes were determined using the KM plotter (SCN2A, ELAVL2, BCL2, MAF, and ZNF532,) to confirm the association between patterns of expression and metastasis risk in ovarian cancer patients." (PMID 38654363, 2024). "The previous study observed a downregulation of the genes SCN2A, ELAVL2, ZNF532, MAF and BCL2 which were identified in ovarian cancer." (PMID 38654363, 2024). "Taken together, in M2 macrophages induced by ovarian cancer, MAF rather than NF-κB appears to be a vital component of the process by which BRD4i causes repolarization of M2 macrophages." (PMID 32184777, 2020). "Next, to validate whether the downregulated genes, such as MAF, GATA6, and DAB2, are affected by epigenetic dysregulation, we treated ovarian cancer cell lines with a pan-HDAC inhibitor, TSA, which mechanistically augments transcriptionally active histone modification." (PMID 37779141, 2023). "As evidenced by CHIP-PCR, we found that the TF binding site (TFBS) of five TFs had binding events to BRD4 after it was cultured with or without CM of ovarian cancer cells, among which PRDM1 and MAF had increasing binding events after CM treatment." (PMID 32184777, 2020).
angioimmunoblastic T-cell lymphoma (4 papers, 2020 to 2023). A mature T-cell non-Hodgkin lymphoma, characterized by systemic disease and a polymorphous infiltrate involving lymph nodes and extranodal sites. "In about 60% of angioimmunoblastic T-cell lymphomas, c-MAF was found to be overexpressed, whereas in MM, aberrant c-MAF, MAFA, and MAFB gene expressions have been described." (PMID 34947882, 2021). "Moreover, c-MAF is overexpressed in 60% of angioimmunoblastic T-cell lymphomas in humans and expression of c-MAF in the T-cell compartment in transgenic mice results in development of T-cell lymphomas." (PMID 33494394, 2021).
autoimmune disease (4 papers, 2019 to 2025). A disorder resulting from loss of function or tissue destruction of an organ or multiple organs, arising from humoral or cellular immune responses of the individual to their own tissue constituents. "We previously tested whether genes coregulated by the “Th17 core” (RORC, STAT3, BATF, IRF4, and MAF) were enriched for gene sets from GWAS of nine autoimmune diseases and three “negative controls” (Alzheimer's, schizophrenia, and type 2 diabetes)." (PMID 30696696, 2019).
myopia (4 papers, 2021 to 2025). "Aberrant TGF-β1 signaling activation by MAF has been implicated in pathological lens growth, a key factor in the development of high myopia." (PMID 40110040, 2025). "Our results establish lens morphological and molecular changes as a characteristic feature of high myopia, and point to the dysregulation of the MAF-TGF-β1-crystallin axis as an underlying mechanism, providing an insight for therapeutic interventions." (PMID 33833231, 2021). "The dysregulation of the MAF-TGF-β1-crystallin axis may be an underlying mechanism that leads to the development of high myopia." (PMID 36979429, 2023). "Mechanistic studies show that the transcription factor MAF plays an essential role in up-regulating β/γ-crystallins in high myopia, by direct activation of the crystallin gene promoters and by activation of TGF-β1-Smad signaling." (PMID 33833231, 2021). "Together, our study identified a previously unrecognized role for MAF-TGF-β1-crystallin axis in pathological growth of lens in high myopia." (PMID 33833231, 2021). "As to the pathological growth of lens in high myopia, apart from the direct regulation of crystallins by MAF, it is also tempting to speculate on the participation of growth factors in this process." (PMID 33833231, 2021). "In high myopia, the aberrant activation of TGF-β1 signaling was attributed to the positive regulation by MAF." (PMID 33833231, 2021). "Taken together, we suppose that in high myopia, NOTCH2 signalling inhibition could accelerate secondary lens fibre cell differentiation by activating CDKN1C, the differentiation initiator, and promote accumulation of β/γ crystallin, the specific structural proteins of LFCs, by activating MAF." (PMID 36717696, 2023).
prostate carcinoma (4 papers, 2017 to 2022). A carcinoma that arises from epithelial cells of the prostate gland. "Weighted gene co-expression network analysis (WGCNA) suggests a set of five dysregulated hub genes (MAF, STAT6, SOX2, FOXO1, and WNT3A) that played crucial roles in biological pathways associated with prostate cancer progression." (PMID 35719950, 2022). "c-MAF is thought to act as a tumor suppressor gene in prostate cancer." (PMID 29757260, 2018). "The NFEF2L2 (NRF2), MAF genes were found to be hypermethylated in all four cancers, while the hypermethylation of NQO gene was only observed in prostate cancer." (PMID 33143142, 2020).
Autoimmunity (3 papers, 2018 to 2025). The occurrence of an immune reaction against the organism's own cells or tissues. "The role of MAF in Th cells and autoimmunity has been extensively explored." (PMID 30671056, 2018).
colon cancer (3 papers, 2021 to 2023). "As shown in the interaction network, immune-related gene PLCG2 and IGF1, which are up-regulated in colon tumor samples, have significantly strong correlation with several TFs: FOXP3, IKZF1, CBX7, LMO2, MEF2C, EPAS1 and MAF." (PMID 33996273, 2021).
Obesity (3 papers, 2013 to 2023). Accumulation of substantial excess body fat. "The FTO gene, located on chromosome 16q12.2, and the MAF gene, located on chromosome 16q22-23, were identified as genes harboring common variants with an impact on obesity predisposition." (PMID 23840443, 2013). "The FTO and MAF genes have been recently described to be major candidate genes for human obesity, and these results have been replicated in multiple populations." (PMID 23840443, 2013).
osteosarcoma (3 papers, 2024 to 2025). A usually aggressive malignant bone-forming mesenchymal neoplasm, predominantly affecting adolescents and young adults. "The study investigating the role of the tumor microenvironment in highly invasive osteosarcoma identified a high expression of CD320 and MAF genes in tumor infiltrating regulatory T cells (Tregs)." (PMID 40565117, 2025).
atherosclerosis (2 papers, 2022 to 2025). A disease characterized by the build-up of fatty material and calcium deposition in the arterial wall resulting in partial or complete occlusion of the arterial lumen. "The protein encoded by the MAF gene is a DNA-bound, leucine zipper-containing transcription factor identified as a novel central regulator of the atherosclerosis/CHD-associated liver network and may be a potential therapeutic target." (PMID 40868093, 2025). "Then, six hub genes (COL1A1, IBSP, CTSD, RAC2, MAF, and THBS1) were obtained through the integration of multisource databases and they were all significantly upregulated in both the osteoporosis and atherosclerosis group compared with the control group." (PMID 35937806, 2022).
Ayme-Gripp syndrome (2 papers, 2021 to 2022). "Another indirect connection is the missense mutations of GSK-3 phosphorylation sites found in MAF (v-maf avian musculoaponeurotic fibrosarcoma oncogene homolog), the causative gene of Ayme-Gripp syndrome, where the facial features are similar to those seen in DS." (PMID 35126052, 2021).
breast tumors (2 papers, 2021 to 2023). "We noticed an inverse relationship between levels of MAF upregulation and those of GGPS1 or FDPS, and an almost exclusive expression of MAF and GGPS1 or MAF and FDPS in breast tumors." (PMID 33670680, 2021).
cholangiocarcinoma (2 papers, 2019 to 2023). A carcinoma that arises from the intrahepatic biliary tree (intrahepatic cholangiocarcinoma) or from the junction, or adjacent to the junction, of the right and left hepatic ducts (hilar cholangiocarcinoma). "In human hepatocellular carcinoma (HCC) and cholangiocarcinoma (CCA) cells, PHB1 inhibits cell growth and negatively regulates the expression of oncogenes c-MYC, MAFG, and c-MAF." (PMID 30886235, 2019).
coloboma (2 papers, 2007 to 2024). An abnormality in which a part of a structure in one or both eyes is missing. "Previous research has linked mutations in genes such as CHX10, MAF, PAX6, PAX2, RX (RAX), SHH, SIX3, OTX2, and SOX2 to phenotypes associated with microphthalmia, anophthalmia, and coloboma (MAC)." (PMID 39129019, 2024).
fatty liver disease (2 papers, 2025). A reversible condition wherein large vacuoles of triglyceride fat accumulate in liver cells via the process of steatosis. "Homeostatic cholesterol biosynthesis is necessary for immune resolution by CD4+ cells in a c-MAF-AP-1-dependent manner, which drives IL-10 production that was shown to be protective against diet-induced fatty liver disease in mice." (PMID 40510344, 2025). "Interestingly, treating LivKO mice with mAF led to a significant reduction in hepatic expression of genes related to inflammation and fibrosis, though having no impact on hepatic steatosis." (PMID 40547297, 2025).
laryngeal squamous cell carcinoma (2 papers, 2021 to 2023). A squamous cell carcinoma that arises from the larynx. "We have shown previously that the overexpressed miR-1290 influences MAF protein levels in LSCC (laryngeal squamous cell carcinoma) cell lines." (PMID 34356658, 2021).
lens diseases (2 papers, 2021 to 2026). "The MAF- TGF-β1-crystallin axis identified in this study may be also highly suggestive of other lens diseases." (PMID 33833231, 2021).
multiple sclerosis (2 papers, 2018 to 2020). A progressive autoimmune disorder affecting the central nervous system resulting in demyelination. "MAF expression has also been associated with multiple sclerosis, a range of cancers including renal cancer, glucagon expression and biosynthesis and autoimmune diabetes." (PMID 30719032, 2018). "An inverse relationship between MAFTRR levels and MAF expression has previously been identified in patients with multiple sclerosis, whereby higher levels of MAFTRR in CD4+ T lymphocyte cells lowers expression of MAF." (PMID 30719032, 2018). "It was previously reported that MAF inhibits Th1 cell differentiation by suppressing the production of IFN-γ, and MAF has been shown to be downregulated in PBMCs from Multiple sclerosis (MS) patients." (PMID 32595646, 2020).
viral infection (2 papers, 2022 to 2024). "In contrast to the gene expression data from A549 following AR enzalutamide or siRNA treatment, viral infection induced down-regulation of MAF with up-regulation of IL6." (PMID 38292196, 2024).
Achalasia (1 paper, 2023). A disorder of esophageal motility characterized by the inability of the lower esophageal sphincter to relax during swallowing and by inadequate or lacking peristalsis in the lower half of the body of the esophagus. "Besides, many co-inhibitory molecules, including PDCD1, HAVCR2, LAG3, ICOS, PRDM1, and MAF, were markedly downregulated in TRM, supporting an activated cell state in achalasia." (PMID 37542039, 2023).
age (1 paper, 2021). A temporal measurement of the time period elapsed since an identifiable point in the life cycle of an organism. "In mice, MAF promotes osteoblast differentiation and may be an important gene for age-related bone disease therapy." (PMID 34921240, 2021).
anaplastic astrocytoma (1 paper, 2024).
B-cell CLL/ (1 paper, 2009).
bladder cancer (1 paper, 2018). "We presented a case study with MAF (MAF BZIP Transcription Factor) gene for bladder cancer as an example, to demonstrate how one can use CAS-viewer to gain insight into comprehensive understanding of molecular complexity existing among splicing, methylation, and miRNA, and its clinical correlation." (PMID 29697367, 2018).
Cirrhosis (1 paper, 2025). A chronic disorder of the liver in which liver tissue becomes scarred and is partially replaced by regenerative nodules and fibrotic tissue resulting in loss of liver function. "MAF expression was almost exclusively seen in healthy LSECs and to a lesser extent in central vein ECs, lymphatic ECs and a small cluster of cirrhosis-specific mesothelial cells." (PMID 40810103, 2025). "To elucidate whether the expression of transcription factor MAF is also altered in human cirrhosis, we analyzed published scRNA-seq data from healthy and cirrhotic human liver samples." (PMID 40810103, 2025). "Notably, at a global level, MAF expression was significantly reduced in ECs from donors with cirrhosis, while it was preserved in the few LSECs that retained a pericentral, midzonal, or periportal expression profile." (PMID 40810103, 2025).
familial hypercholesterolemia (1 paper, 2026). An inheritable form of hyperlipidemia, in which there are excess lipids in the blood.
glioma (1 paper, 2020). A benign or malignant brain and spinal cord tumor that arises from glial cells (astrocytes, oligodendrocytes, ependymal cells). "XL388 downregulated MAF bZIP transcription factor G (MAFG) and inhibited Nrf2 signaling, causing oxidative injury in glioma cells." (PMID 33159013, 2020).
gout (1 paper, 2018). A condition characterized by painful swelling of the joints, which is caused by deposition of urate crystals. "The MAF bZIP transcription factor (MAF) is a strong candidate gene for involvement in serum urate control and gout." (PMID 30719032, 2018). "Additionally MAF has been shown to regulate antioxidant and apoptotic pathways that are required for NLRP3 inflammasome activation implicated in chronic kidney disease and gout." (PMID 30719032, 2018).
insulinoma (1 paper, 2023). "Further, c-MAF- and MAFB-mutant mice exhibited similar phenotypes to human patients, suggesting the need to create conditions conducive to insulinoma development." (PMID 37895232, 2023). "Notably, differences exist between c-MAF- and MAFB-mutant mice and MAFA-mutant mice in terms of their proclivity to develop insulinoma, a typical disease in humans." (PMID 37895232, 2023).
oral cancer (1 paper, 2024). "This polymorphism may influence the motif for potential binding of transcription factor LUN-1, MAF oncogene family, and a cancer stem cell regulator NK2 homeobox 1 (Nkx2), previously associated with oral cancer in vitro." (PMID 38850110, 2024).
pneumonia (1 paper, 2024). An acute, acute and chronic, or chronic inflammation focally or diffusely affecting the lung parenchyma, caused by an infection in one or both of the lungs (by bacteria, viruses, fungi, or mycoplasma.). "SCENIC analyses predicted higher MAF and MAFB activities in the Mo-Mac cluster compared to other clusters, further supporting that the airspace of human pneumonia lungs contains Mo-Macs that are transcriptionally similar to mouse Ly6G+ Macs." (PMID 39093958, 2024).
sarcoma (1 paper, 2017). A usually aggressive malignant neoplasm of the soft tissue or bone. "Note that one homozygous deletion in sarcoma abolishes both MAF and MAFTRR, suggesting MAFTRR may still have other functions." (PMID 29089486, 2017).
ulcerative colitis (1 paper, 2024). An inflammatory bowel disease involving the mucosal surface of the large intestine and rectum. "The aim of this study was to explore whether MAF bZIP transcription factor B (MAFB) might alleviate ulcerative colitis (UC) in dextran sulfate sodium (DSS)‐induced mice and LPS‐induced IEC‐6 cells." (PMID 39172054, 2024).